TLR4 (toll like receptor 4)
Diseases named in the same sentence as TLR4 in open-access papers (continued):
Sharing a sentence is not in itself a finding about the gene and the disease.
Sepsis (continued). "All the data revealed that serum decreased miR-103 in sepsis patients serves as a promising noninvasive diagnostic biomarker and may be involved in the pathogenesis of sepsis by regulating inflammatory responses via targeting TLR4." (PMID 32455124, 2020). "The important role of TLR4 in sepsis combined with our study results led us to deduce that miR-103 might inhibit the inflammatory response of sepsis by targeting TLR4." (PMID 32455124, 2020). "Therefore, TLR4 has become a target for drug design and development, and some such drugs for the treatment of lung inflammation, sepsis, and rheumatoid arthritis have already entered preclinical and clinical trials." (PMID 32397494, 2020). "Quercetin in the QX1 formula may play an important role in preventing myocardial dysfunction via the TLR4/NF-κB signaling pathway during sepsis." (PMID 32908632, 2020). "TLR4 and TLR2 are involved in the control of splenic DC apoptosis during polymicrobial sepsis, suggesting that modulation of DC-specific TLR4/TLR2 signaling may be a new therapeutic strategy for the treatment of sepsis." (PMID 32197507, 2020). "It has been reported that in the rats septic model injected by LPS for 24 h, the expression of miR-146a increased, which inhibited the activation of toll-like receptor 4/nuclear factor kappa-B (TLR-4/NF-κB) signaling pathways and alleviated the cardiomyocytes apoptosis and injury caused by sepsis." (PMID 32908879, 2020). "Similarly, another TLR4 antagonist designated Resatorvid (TAK-242) was also studied in the treatment of sepsis and reached Phase III of the clinical trials, however it failed to attenuate inflammation in septic patients." (PMID 33679711, 2020). "Soluble MD2 in plasma of patients with severe sepsis is known to promote the LPS response in TLR4-expressing epithelial cells of lungs and other organs 29, suggesting that soluble MD2 could be a pivotal mediator of organ inflammation." (PMID 32210720, 2020). "Research is ongoing to determine whether TLR4 modulation may still be useful in combination therapies, or in inflammatory conditions other than sepsis." (PMID 31491842, 2019). "Inhibition of TLR4 activation impairs bacterial clearance during sepsis." (PMID 31348811, 2019). "It is unknown at this stage if elevated levels of thrombin in sepsis could trigger upregulation of surface TLR4 expression in canine platelets and, thereby, increases platelet response to endotoxins." (PMID 31307465, 2019). "We next investigated whether TSLP is involved in sepsis in a TLR4-dependent manner and thus focused on biological consequences of TSLP induced by LPS or E. coli in macrophages." (PMID 31480519, 2019). "Thus, it can be deduced that the inflammatory action of MLN DCs in sepsis, via IL-1β, is dependent upon mediation via TLR4 and/or HMGB1." (PMID 31323786, 2019). "Baseline monocyte and neutrophil TLR4 expression is increased in adult sepsis." (PMID 31612119, 2019). "Cyclooxygenase and TxA2 pathways in TLR4-mediated platelet activation may present novel therapeutic targets in dogs with sepsis." (PMID 31307465, 2019). "Because platelet activation mediated by TLR4 may account for the interplay between sepsis and thrombosis in dogs, a better understanding of platelet TLR4 expression and platelet response to LPS, is needed." (PMID 31307465, 2019). "It should be noted that many diabetes patients are subjected to infection or sepsis, in which the TLR4 pathway may be activated to a certain extent." (PMID 29850615, 2018). "TLR4 plays an essential role in host defense against low-grade polymicrobial sepsis by mediating the migratory and/or phagocytic functions of neutrophils, attenuating inflammation, reducing the generation of reactive oxygen species (ROS), and enhancing bacterial clearance." (PMID 29977913, 2018).
Sepsis (continued). "We have used initial tlr4 mRNA expression levels from sepsis patients in a dynamic model in order to describe the distribution of TLR4 within the cell surface compartment (pro-inflammatory role), or intracellularly (anti-inflammatory and signal termination functions)." (PMID 29996939, 2018). "Eritoran that blocks LPS from binding to TLR4/MD-2 complex was used in phase III clinical trial to evaluate whether it could be able to reduce sepsis-induced mortality." (PMID 29686833, 2018). "During sepsis, endotoxin lipopolysaccharides (LPS) activate toll-like receptor 4 (TLR4) signaling pathway and further induce translocation of nuclear factor-kappa B (NF-kappa B) to modulate expression of pro-inflammatory genes, including TNF-α, IL-6, and IL-1β." (PMID 30083155, 2018). "Indeed, weak agonists, as Bradyrhizobium LPS has shown to be, are typically desired to be used as adjuvants in vaccine production, whereas antagonists are being sought as inhibitors of TLR4-dependent signaling to fight against sepsis." (PMID 30154796, 2018). "There is limited evidence thus far to suggest that toll-like receptor 4 (TLR-4) and platelet-leukocyte aggregate (PLA) formation may be implicated in the development of sepsis-associated thrombocytopenia." (PMID 29734352, 2018). "The mechanism of these SND protective effects on sepsis may be through downregulation of adrenal TLR4 expression." (PMID 30018657, 2018). "The main objective of this work was to study mechanisms that could contribute to the development of sepsis-associated thrombocytopenia focusing on the MMP-2/-9 platelet dependent pathway, platelet TLR-4 signalling and PLA formation in sepsis." (PMID 29734352, 2018). "The beneficial actions of leptin during sepsis could be mediated by regulation of the expression of the endotoxin receptor toll-like receptor-4 (TRL-4) and modulation of its activity." (PMID 30618812, 2018). "In the early stages of toll-like receptor 4- (TLR4-) mediated sepsis, SIRT1 rapidly accumulated at TNF-α and IL-1β promoter regions and deacetylated the RelA/p65 lysine 310 site and nuclear histone H4 lysine 16 sites, ultimately promoting NF-κB transcription termination." (PMID 30533222, 2018). "Therefore, novel therapeutic target responding to TLR pathogens from Gram-positive bacteria and viruses, affecting redundant SIRS pathways other than MD-2 or TLR4, is required in the alternative treatment of sepsis patients." (PMID 28145460, 2017). "It is unclear whether it was the LPS in the blood or another substance that stimulated this response as certain proteins that may stimulate platelets in a TLR4-dependent manner are also released into the blood during sepsis, for example, HMGB1." (PMID 29170605, 2017). "TAK-242 (Resatorvid) is an anti-sepsis SMI that targets TLR4 signaling pathways." (PMID 28769820, 2017). "Overall, we demonstrated that the disruption of neurotransmitters, impairment of neurongenesis and activation of astrocytes coupled with concomitant neuro-inflammation via HMGB-1/TLR4 signaling pathway were the potential pathogenesis of cognitive impairment in sepsis survivors." (PMID 28059131, 2017). "What is more, TLR4‐signalling blockade in various sepsis models blunts or even abolishes AKI." (PMID 27602552, 2017). "Development of sepsis caused by Gram-negative bacteria is associated with production of lipopolysaccharide (LPS), which activates the Toll-like receptor 4 (TLR4) pathway." (PMID 28442605, 2017). "This may be due to the increased immune activation of 576a LPS and activation of TLR4-dependent bacterial clearance and uptake by the liver during sepsis." (PMID 28592242, 2017). "Failure to curtail the TLR4-mediated immune response can lead to pervasive tissue injury and may give rise to immunopathology such as sepsis, autoimmune diseases, metabolic diseases, neurodegeneration and chronic inflammation." (PMID 27628304, 2017).
Sepsis (continued). "Sepsis risk was associated with TLR4 (toll like receptor 4) SNPs, rs4986790 and rs4986791, but not the SERPINE1 [Serpin Peptidase Inhibitor, Clade E (Nexin, Plasminogen Activator Inhibitor Type 1), Member 1] rs1799768 polymorphism." (PMID 29340067, 2017). "In this review, we explore how one specific TLR, Toll‐like receptor 4 (TLR4), may cause acute kidney injury (AKI) in sepsis." (PMID 27602552, 2017). "Among all TLRs, TLR2, and TLR4 are the two notable contributors to the pathogenesis of sepsis." (PMID 28769820, 2017). "Evidence of TLR4 activation having a negative influence on outcomes following severe infection has been demonstrated in previous studies using mouse models, showing that blockade of TLR4 inhibited systemic inflammatory responses in sepsis, which reduced the disease severity and lethality." (PMID 28484092, 2017). "Additional studies are needed to know if our results mimic some in vivo condition and whether TLR4 could become a new target to modulate the hemostatic disorder of sepsis." (PMID 28957360, 2017). "For TLR4, two frequently co-segregating polymorphisms (Asp299Gly and Thr399Ile) have been shown to increase the risk of sepsis, Gram-negative infections and severe malaria." (PMID 28241747, 2017). "Moreover, reduced expression of TLR4 in the liver improves the regeneration of this organ in rats subjected to CLP induced sepsis." (PMID 27293313, 2016). "Notably, the magnitude of LPS-stimulated HLA-DR expression determined the phagocytosis of CD16- monocyte in TLR4+896A/G and CD14-159C/T variant allele carriers with severe sepsis." (PMID 27861595, 2016). "Thus, after CLP induced polymicrobial sepsis at 24 h and 48 h, the liver protein levels of TLR4 and of AOAH were determined and shown markedly decreased in CETP as compared to WT." (PMID 27293313, 2016). "TLR4 activation in sepsis leads to mitochondrial structure damage." (PMID 27589725, 2016). "Among TLR4+896A/G variant allele carriers with severe sepsis, a significant negative correlation was noted between plasma IL-10 levels and LPS-stimulated HLA-DR expression on CD16- monocyte." (PMID 27861595, 2016). "Therefore, a better understanding is needed of sepsis in general and the role of TLR-4 agonists in this process before new therapeutics against sepsis is developed." (PMID 27064683, 2016). "In our TLR4+896A/G variant allele carriers with severe sepsis, a negative correlation was noted between plasma IL-10 and LPS-stimulated CD16- (classical) monocyte HLA-DR expression." (PMID 27861595, 2016). "As the in vivo experiments revealed an influence of CETP on endotoxemia and CLP induced sepsis, we asked whether this would have an impact on cell activation in the TLR4 signaling cascade." (PMID 27293313, 2016). "Given the role of TLR4 in the activation of the proinflammatory response during infection, pharmacological approaches targeting TLR4 have been developed with the aim to control host's deleterious proinflammatory response called “cytokine storm” occurring in the early phase of sepsis." (PMID 27293318, 2016). "MyD88 is responsible for most canonical TLR signaling, such as TLR4-mediated sensing of LPS, as well as for canonical IL-1 signaling, and is thus broadly required for multiple cellular responses during polymicrobial sepsis." (PMID 26790027, 2016). "Both TLR4+896A/G and CD14-159C/T variant allele carriers shared common increased CD16+ (non-classical, inflammatory) monocyte subset–related mechanisms for increased severe sepsis risk." (PMID 27861595, 2016). "The up-regulated TLR4 expression-increased TNFα/iNOS/nitrite levels and subsequently systemic acute inflammatory status (high plasma sCD14 and total NO levels) resulted in severe sepsis among them." (PMID 27861595, 2016). "Some studies have linked TLR4 polymorphisms to an increased susceptibility to sepsis due to gram-negative infection; other studies failed to confirm this." (PMID 27293318, 2016).
Sepsis (continued). "Whereas essential TLR4 activation is required to facilitate infection control, excessive TLR4 stimulation by LPS may result in serious consequences, such as sepsis, multiple organ dysfunction (MODS) and shock." (PMID 27542278, 2016). "We hypothesize that plasma concentration of CETP influences the TLR4 expression attenuating the inflammatory response induced by LPS and polymicrobial sepsis." (PMID 27293313, 2016). "In addition to LPS, several endogenous danger-associated molecular patterns (DAMPs), including the newly identified peroxiredoxin-1 (Prdx1), can also interact with CD14/TLR4 and elicit severe sepsis-like response." (PMID 27142532, 2016). "Unfortunately, the results of clinical trials with molecules targeting TLR4 were disappointing, suggesting that immune suppression, which follows the “cytokine storm,” represents the leading process in the progression of sepsis." (PMID 27293318, 2016). "The inhibition of free hemoglobin effects as a TLR-4 independent noxious mechanism of LPS might be a good candidate for sepsis therapy as innate immune system function important for host defense is likely not altered." (PMID 27759044, 2016). "LPS interacts with the Toll-like receptor-4 (TLR-4), along with other accessory components, to generate a battery of pro-inflammatory cytokines and lipid mediators that promote a systemic inflammatory response–the hallmark of sepsis." (PMID 27064683, 2016). "We speculate that Smaducin-6 shows the highest efficacy in innate immune cells residing in the lymphatic-vessel-rich organs, in which Pellino-1-mediated TLR4 signaling plays the most important pathophysiological roles in sepsis." (PMID 25766838, 2015). "The findings of the current study reinforce the role of TLRs in the pathogenesis of sepsis and suggest that blockade of TLR2 or TLR4 may be a useful therapeutic approach to control systemic inflammation, organ injury and lethality in polymicrobial sepsis." (PMID 26147469, 2015). "Taking this into consideration, TLR4 may directly alter the interaction between MV and lungs that were preinjured by sepsis." (PMID 26161235, 2015). "Additionally, it is also noteworthy that other TLRs, such as TLR2 and TLR4, present pivotal roles in the regulation of sepsis-induced cardiac inflammation during sepsis." (PMID 26448624, 2015). "Indeed, we found that Smaducin-6 directly binds to Pellino-1 and disrupts three important signaling complexes in the TLR4 pathway, eventually resulting in the inhibition of pro-inflammatory cytokines as well as apoptosis in sepsis models." (PMID 25766838, 2015). "Therefore, our preclinical experiments strongly suggest that there exists a therapeutic window in which to use anti-TLR2 or anti-TLR4 mAbs with antibiotics in patients with ongoing sepsis." (PMID 26147469, 2015). "Vigorous responses through TLR4 may result in harmful outcomes, such as excessive inflammatory responses during sepsis, tissue injury, and allergic diseases." (PMID 26177520, 2015). "This collectively suggests an active participation of TLR4 in the response of HSPCs to sepsis." (PMID 26272069, 2015). "However, an uncontrolled response of TLR4 signaling against LPS endotoxin can result in the inflammatory disease called sepsis." (PMID 26198237, 2015). "However, the uncontrolled response after LPS recognition by TLRs results in sepsis and thus inhibiting TLR4 and TLR2 mediated signaling is an effective therapy for sepsis." (PMID 26198237, 2015). "The present study addressed the question of whether the putative regulatory TLR4 rs11536889 genotypes are related to organ failure in critically ill patients with sepsis." (PMID 24950711, 2014). "Interestingly, the presence of a specific TLR-4 mutation (D299G) in humans, which impairs LPS signaling, has not been shown to influence TNF-α, IL-6, and IL-10 levels in sepsis." (PMID 25575158, 2014).
Sepsis (continued). "TLR4 antagonists as new treatments for sepsis and neuropathic pain might unexpectedly transiently enhance pain by impairing peripheral opioid analgesia." (PMID 24499354, 2014). "Understanding how TLR4-mediated autophagy-like degradative processes are regulated in the liver and hepatocytes is important if we are to more fully understand how and why organs such as the liver fail during sepsis." (PMID 24683544, 2014). "Accordingly, these previous investigations support the assumption that TLR4 rs11536889 GG sepsis patients present severe organ dysfunction (as measured using SOFA scores) because of attenuated TLR4 proinflammatory signaling in response to LPS compared to C allele carriers." (PMID 24950711, 2014). "This study aimed to investigate whether organ failure in sepsis patients is related to the TLR4 rs11536889 genotype." (PMID 24950711, 2014). "This study aimed at exploring whether the putative regulatory TLR4 rs11536889 genotypes relate to organ failure severity in critically ill patients with sepsis during their time in the intensive care unit." (PMID 24950711, 2014). "In summary, our data show that TLR4 signaling is important for the development of septic AKI and that treatment with a TLR4 inhibitor is able to reverse a manifest reduction in renal function caused by sepsis." (PMID 25182709, 2014). "Different opinions have been made in previous studies about the expression patterns and the role of proinflammatory cytokines in sepsis that attracted our attention towards qualitative properties of TLR4 and JAK/STAT signalling pathways using computer-aided studies." (PMID 25255432, 2014). "This study was designed to evaluate whether the TLR4 and cluster CD14 gene polymorphisms are associated with susceptibility to sepsis." (PMID 25394369, 2014). "One of the main objectives with the current study was to investigate whether TLR4 inhibition is effective in attenuating or reversing renal dysfunction even after sepsis has developed." (PMID 25182709, 2014). "TLR4 and JAK/STAT mediated signalling was designed in the current study by incorporating previous experimental studies associated with interaction of entities and their overall effect in case of sepsis." (PMID 25255432, 2014). "TLR4 signaling pathway activation by LPS plays a major role in sepsis pathogenesis." (PMID 24950711, 2014). "The potential of TLR4 antagonists for sepsis therapy has long been recognized." (PMID 25056632, 2014). "Several studies have shown that polymorphisms in TLR4 and CD14 genes may relate to the susceptibility with some infection induced diseases, e.g. sepsis, but this is controversial." (PMID 25394369, 2014). "Furthermore, we put forward the notion that bacteria probably already produce inhibitors of TLR4 signaling, making these bacterial products interesting molecules to investigate for future sepsis therapies." (PMID 25056632, 2014). "In particular, HCO3− reabsorption is inhibited by the direct effect of LPS on TLR4, and this may contribute to sepsis-induced acidosis." (PMID 25182709, 2014). "Given the key role of TLR4 in both ventilator induced lung injury and bacterial infection or sepsis, we speculate that the lung protective ventilation might have suppressed TLR4 mRNA expression in our NG group." (PMID 23622115, 2013). "However, increased TLR4 expression in NK cells in patients with sepsis was accompanied by a reduced IFN-γ response to LPS." (PMID 23372571, 2013). "This provides the opportunity to dissect the relative roles of NOD1 and TLR4 in more complex models of sepsis and may lead to new therapeutic approaches in septic shock and related microvascular pathologies including acute lung injury." (PMID 22870324, 2012). "In sepsis caused by Gram-negative bacteria, endotoxin (LPS) activates the immune system through TLR4 and induces activation of macrophages that produce inflammatory mediators." (PMID 22654663, 2012).